CCL3 (C-C motif chemokine ligand 3)
Diseases named in the same sentence as CCL3 in open-access papers (continued):
Sharing a sentence is not in itself a finding about the gene and the disease.
tumor (continued). "Accordingly, ablation of the cognate IL-33 receptor St2 limits tumor growth, and reduces mast cell-dependent production and release of the macrophage-attracting factors Csf2, Ccl3, and Il6." (PMID 31227713, 2019). "In this study, we present data showing that a chemokine CCL3 derivative, eMIP, administered after HT treatment produces marked tumor growth inhibition and dramatic reduction of distant metastases." (PMID 31717914, 2019). "Studies show that along with CCL5, CCL3 mediated fibroblast accumulation in the tumor microenvironment." (PMID 31835892, 2019). "The genes that were overexpressed in both senescent thyrocytes and at least one tumor cell line included genes coding for: the chemokines CCL3 and CCL-4, the cytokine IL-1β, the matrix-related protein SPP1, and the enzyme PTGS2." (PMID 31113465, 2019). "In glioma, the presence of CCL3 in the tumor tissue was found to correlate with a higher tumor grade." (PMID 31847343, 2019). "Tumor‐derived chemotactic factors such as Ccl2, Ccl3, Ccl5, and Ccl7 are known to recruit macrophages to the growing tumor." (PMID 29047229, 2018). "CCL3 has emerged as a potent activator of both innate and adaptive responses, playing a critical role in recruiting of immune cell population into the tumor." (PMID 29410666, 2018). "CCL5 can attract T lymphocytes to the tumor, while CCL3 is able to recruit neutrophils into the tumor." (PMID 29755464, 2018). "The increase in the number of tumor-infiltrating NK cell in Salmonella-treated group is consistent with the increment in Ccl2, Ccl3, and Ccl5 gene expression observed in these groups, since one function of these chemokines is the recruitment of NK cells." (PMID 29410666, 2018). "Our results provide definitive evidence that CCL3 is relevant for oral carcinogenesis, regulating tumour cell interplay and neoplastic cell behaviour." (PMID 28881626, 2017). "In contrast, CCR5-/- mice treated with 4NQO exhibited a reduced incidence of tumour formation and lower histopathological scores, which was similar to the CCL3-/- mice." (PMID 28881626, 2017). "Depletion of CD8+ T-cells reduced the antitumor effect of CCL3 administration indicating radiation induced recruitment of this cell population to the tumor site." (PMID 28638385, 2017). "Our data suggest that factors derived from tumor cells are also critical for CCL3-induced TDLN accumulation of leukocytes." (PMID 29109732, 2017). "In the current study, we aimed to distinguish the effect of CCL3 on early antitumor immune priming in the LN from the later adaptive immune responses at the primary tumor site." (PMID 29109732, 2017). "The results showed that several genes were highly expressed in tumor, including Cxcl2, Ccl2, Ccl3, Ccl4, and Ccl5." (PMID 28432279, 2017). "Although these studies were primarily focused on CCL4, the production of CCL3 was also significantly increased in their tumor system." (PMID 29109732, 2017). "Comparatively, the SCC tongue tumour formation was more prominent in the WT than the CCL3-/- mice treated with 4NQO." (PMID 28881626, 2017). "This was, for instance, the case with CCR5 which, with the two ligands i.e. CCL2 and CCL3, formed the two ligand-receptors pairs that exhibited the largest increase in correlation when comparing tumor to normal tissues." (PMID 28821810, 2017). "Our results are corroborated by previous findings showing that tumours from CCL3-/- and CCR5-/- mice presented reduced vascularisation." (PMID 28881626, 2017). "The CCR5 receptor is present on the surface of tumor cells and is responsible for CCL3-mediated cell motility and angiogenesis." (PMID 26713602, 2016). "In conjunction with NF-κB, β-catenin enhanced expression of immunosuppressive interleukin-10 and suppressed antitumoral CCL3, indicating that β-catenin can induce a favorable tumor microenvironment." (PMID 26776161, 2016).
tumor (continued). "In recent years, EGFR-targeted therapy has been reported to not only inhibit tumor cells, but also reduce the secretion of GM-CSF, CCL3, TGF-α, bFGF, and VEGF, further affecting the tumor microenvironment." (PMID 27683110, 2016). "CCL3 can recruit and activate monocytes and is involved in anti-tumor activities as a Th-1 cytokine and increasing NK cell cytotoxicity." (PMID 27169366, 2016). "The biological activity of CCL3 fused to other proteins has been determined for fusions with a tumor antigen, HIV-1 gp-120, mCherry fluorescent protein, and hemagglutinin from influenza virus." (PMID 26494531, 2015). "In FOXM1 transgene model, elevated tumor formation was associated with persistent pulmonary inflammation, macrophage infiltration and increased expressions of CXCL5, CXCL1 and CCL3." (PMID 25788272, 2015). "The secretion of chemokines by LRP1-deficient macrophages is enhanced (especially CCL3), resulting in an increased number of tumor-associated macrophages (TAM) in the tumor site." (PMID 26617523, 2015). "Whereas HCC induced by N-nitrosodiethylamine treatment occurred more frequently in both CCL3- and CCR1-deficient mice compared with control mice, tumor burden was dramatically reduced by CCL3 or CCR1 deficiency." (PMID 24646914, 2014). "Of interest, we identified an enrichment of genes involved in the CXCR4 signaling pathway or in the interactions between the CLL tumor cells and their microenvironment (CCL3, CCL4, and CD49d)." (PMID 24883311, 2014). "First, targeting by CCL3 has been shown to induce protection against tumor development in mouse models, and CD8+ T cells were crucial for the protection." (PMID 25122197, 2014). "In skin tumor-bearing mice, CCR5 was preferentially expressed on tumor-infiltrating Treg cells, which seemed to be recruited to the tumor via its ligands, CCL3, 4, and 5 that was produced by myeloid-derived suppressor cells (MDSCs)." (PMID 23874336, 2013). "As shown in previous studies, the CCR5 receptor is present on the surface of tumor cells and is responsible for CCL3-mediated cell motility." (PMID 24047437, 2013). "In contrast to IL8 and IL1β which promote tumor growth, CCL3 possesses antitumor effects in preclinical models and has been investigated as a tumor immunotherapy strategy." (PMID 23762239, 2013). "Cytokine-treated cells were used to evaluate cell surface phenotype, expression of molecular determinants of lymphoid/NK cell differentiation, secretion of IFN-γ, GM-CSF, TNF-α and CCL3/MIP-1α, and cytolytic activity against NK-sensitive tumour cell targets." (PMID 19712464, 2009). "Among them, MCP-3 has been shown to augment monocyte anti-tumor activity while CCL3/MIP-1α and MIP-1β represent potent pro-inflammatory factors with chemotactic properties for neutrophils and DC and NK cells." (PMID 17222352, 2007). "Ligand-receptor interaction analysis further identified predicted interactions between CCR5+ CD8+ T cells and tumor-associated myeloid cells, with elevated expression of CCL3 and CCL4 observed in myeloid populations from non-responsive tumors." (PMID 42278489, 2026). "Patient‐specific analysis of amplitude and duration of cytokine and chemokine persistence in CSF of humans after SCI revealed that proinflammatory chemokines CXCL1 and CCL3 tend to positively correlate with length of tumor, whereas anti‐inflammatory cytokine IL‐10 correlates negatively." (PMID 41147460, 2026). "CCL3 showed strong positive correlations with immune cell infiltration, particularly macrophages (Cor = 0.72, p < 0.001) and neutrophils (Cor = 0.74, p < 0.001), suggesting its role in shaping an immunosuppressive tumor immune microenvironment (TIME)." (PMID 42004887, 2026). "Furthermore, they found that both soluble CCL3 and CCL3-secreting radiated tumor vaccine can suppress the progression of tumors in a spatial-dependent manner." (PMID 41153795, 2025). "Additionally, they found that CCL3 increased the percentages of CD45+ leukocytes in the MC38 tumor cells." (PMID 41153795, 2025).
tumor (continued). "Although the majority of studies draw a positive connection between the upregulation of CCL3 and tumor development, some studies found the opposite or indicated that lower levels of CCL3 might also lead to an elevated cancer risk." (PMID 41153795, 2025). "In models of lung cancer, genetic knockout of progranulin (PGRN)-a protein known to suppress immune responses and promote tumor progression- resulted in robust upregulation of CCL3 in CD8+ T cells, correlating with enhanced infiltration, proliferation, and effector function." (PMID 41153795, 2025). "The authors initially identified CCL3 as a factor suppressing tumor growth in vivo; however, in contrast to CCL7, their screening approach under anti-PD-1 therapy suggests that it may also play a role in driving immune cell exclusion from the tumor site." (PMID 39837825, 2025). "The tumor volume was significantly larger in the CCL3-oe group than in the shCCL3 or CCL3-NC group." (PMID 39953613, 2025). "Additionally, chemokines such as CXCL1, CXCL2, CXCL5, CCL2, and CCL3, produced by MAFs, play a role in attracting pro-tumor MDSCs to inhibit CD8+ cells." (PMID 40136652, 2025). "Taken together, the increased expression of endothelial Ccl2, Ccl3, and Ccl4 is necessary for leukocyte transmigration into the lung tissue in the context of virus- or bacteria-induced inflammation, autoinflammation, and tumor-promoting metastasis." (PMID 40111902, 2025). "Cells in the dominant subcluster (Neu_0, Neu_1, Neu_2, and Neu_5) with high expression of Ccl3 and Cstb defined as tumor‐specific neutrophils, which were enriched in the NPs group and exert pro‐tumor effects with a similar expression pattern of Cd274, Vegfa, and Lgals3." (PMID 39761175, 2025). "These seemingly contradictory results may reflect differences in disease stage, tumor models, or experimental methods, but together they underscore the complex role of CCL3 in cancer biology and its potential as both a biomarker and therapeutic target." (PMID 41153795, 2025). "Although CCL3 can enhance local immune evasion, its recruitment of these suppressive cells can diminish effector T cell function and impair tumor cell recognition and clearance, thereby promoting tumor growth and metastasis." (PMID 41376630, 2025). "Moreover, reduced expression of CCL3 has the potential to contribute to the creation of an immunosuppressive tumor microenvironment leading to tumor progression." (PMID 40484866, 2025). "This immunomodulatory role of CCL3 has also been observed in other tumor types." (PMID 41153795, 2025). "We therefore hypothesize that CCL3 functions as a molecular bridge linking tumor biology with neurotoxicity." (PMID 41153795, 2025). "CCL3 has been reported to influence tumor progression by attracting CCR5+ Tregs within the TME." (PMID 41246306, 2025). "Taken together, reduced CCL3 levels in PBMCs a reflects a systemic immune dysregulation, reduced immune cell recruitment to the tumor, potentially diminishing the efficacy of the anti-tumor activity against CRC cells promoting tumor growth and metastasis." (PMID 40484866, 2025). "Notably, the interaction between αEβ7 on TILs and E-cadherin on autologous CCL3-producing tumor cells facilitates CCR5 recruitment at the immunological synapse." (PMID 41479900, 2025). "The chemokines CCL2 and CCL3 recruit pro-tumor macrophages into the TME." (PMID 38742117, 2024). "CCL3 (MIP-1ɑ) was also negatively correlated with tumor burden (r=-0.6093, p = 0.0466)." (PMID 39623404, 2024). "Furthermore, proinflammatory cytokines including CXCL9, TNF-α, CCL4, and CCL3 were also upregulated in the tumor following the combined therapy, further demonstrating the change in the immune environment." (PMID 38705987, 2024). "Interestingly, the proportion of the Mac_MEG3 cluster in tumour samples was found significantly increased, while Mac_FCN1 and Mac_CCL3 clusters were significantly dominant in normal samples." (PMID 39548559, 2024).
tumor (continued). "Notably, M1 macrophages induced by IL-9 recruit anti-tumor immune cells into the tumor tissue through the chemoattractant macrophage chemokines CCL3/4 and CXCL9/10, thereby triggering anti-tumor immunity." (PMID 38892411, 2024). "In both cases, KCs represented the majority of macrophages in normal liver, but a minor subset in tumoural liver, and expressed higher ID3, lower SIRPA and higher chemokine (CCL4, CCL3) and cytokines genes (IL18) in comparison to CD14+TIM4− tumour-associated macrophages." (PMID 38326607, 2024). "Additionally, in silico tumor simulations demonstrated that CCL3 and CCL4 attract CTLs into the tumor, and the newly arriving CTLs amplify chemokine production and promote a positive feedback loop of recruitment." (PMID 38709823, 2024). "The directed activation of neutrophils towards a suppressive phenotype leads to overall immunosuppression as these tumor-associated neutrophils inhibit T cell and NK cell functions, produce chemokines (CCL2, CCL3, and CCL5), and promote tumor growth and angiogenesis." (PMID 39768223, 2024). "Ccl3 and Ccl4 were the most upregulated genes related to the regulation of cell communication in shNKX2‐1 tumor‐infiltrated neutrophils when compared to the shCtrl tumor‐infiltrated neutrophils, which was consistent with our initial observations." (PMID 39113226, 2024). "Tumor-derived CCL3 induces MBD by affecting bone resorption and formation." (PMID 38690165, 2024). "Regarding changes in the mRNA expression of T cell-recruiting chemokine genes, a considerable increase was noted in Ccl3 expression in mouse tumor tissues after PT-100 or combination therapy, whereas Cxcl10 expression was substantially elevated in the PT-100, anti-PD-1 group, and combination groups." (PMID 38672409, 2024). "Furthermore, the concentration of HIF-1α in the tumor showed a significant positive correlation with CCL3 and IL-1β (p (R2) 0.007 (0.47); p (R2) 0.011 (0.38)." (PMID 38273861, 2023). "Previous studies have shown that CCL3 can promote anti‐tumour immune response." (PMID 37775993, 2023). "These genes include markers of alternative macrophage polarization (Arg1, Cd163), monocyte chemoattractant Ccl6, and ligands for CCR2 (Ccl2, Ccl7, Ccl12) and CCR5/1 (Ccl3, CCl4, Ccl9) suggesting that F4/80+ cells in these tumours represent an increase in TAM2‐like myeloid cells." (PMID 35924447, 2023). "Chemokines such as IL-8, CXCL6, and CCL3 attract neutrophils to tumor sites." (PMID 37376417, 2023). "Ccl3 induced by administration of the antimitotic chemotherapy drug docetaxel (DTX) promoted proinflammatory macrophage polarization to suppress tumor progression and increased DTX chemosensitivity in breast cancer via the CCR5-p38/interferon regulatory factor 5 pathway." (PMID 37198402, 2023). "Moreover, immunohistochemical staining was performed to profile the localization of CCL3 protein in ICC tumor and adjacent liver tissues." (PMID 36691046, 2023). "However, some studies have shown CCL3 is overexpressed in a variety of tumour tissues and promotes tumours growth, and when applying an anti‐CCL3 neutralizing antibody, tumour growth reduction was observed." (PMID 37775993, 2023). "In addition, IFNγ-driven increased expression of chemokines in tumors of Dox-treated mice, such as CCL2, CCL3, CCL5, and CXCL16 has been associated with enhanced recruitment of CD8+ T cells to tumors and reduced tumor progression." (PMID 37478172, 2023). "Tumor-infiltrating MDSCs could also recruit CCR5+ Tregs to the tumor site through releasing CCR5 ligands CCL3, CCL4, and CCL5 to promote tumor growth in a B16 melanoma model." (PMID 35267547, 2022). "Of note, knockout of the CCL3 gene retarded tumor cell proliferation." (PMID 35935327, 2022).
tumor (continued). "In summary, our data support a model by which cancer-driven protumoral myelopoiesis is regulated by a circuit in which tumor derived factors induce the production of CCL3 and CCL4 and other CCR1 and CCR5 ligands that, by engaging CCR1 and CCR5, autocrinally promote their differentiation into MDSCs." (PMID 35064009, 2022). "After CCL3 interference, the tumor proliferation in HT29 cells was retarded." (PMID 35935327, 2022). "CCL3 and other CC chemokines have complex roles in the tumour microenvironment." (PMID 35064782, 2022). "Interestingly, some reports have proven that patrolling monocytes can recruit large numbers of NK cells to tumor sites, especially metastatic tumor lesions, through the release of cytokines, such as CCL3, CCL4, and CCL5 47-49." (PMID 36438484, 2022). "As a result, it can be speculated that more tumor-specific T cells will appear, contributing to the anti-tumor activity of CCL3." (PMID 36654820, 2022). "Thus, expanding these cells with IL-3/anti-IL-3 therapy increases the CD8 T-cell recruitment in melanoma tumors and delays the tumor growth in a CCL3/CCL4-dependent manner." (PMID 36429101, 2022). "Twenty-five common tumor-specific intercellular communications were identified in more than four datasets, mainly involved in intercellular communication from other cells to Mono/Macro, including CCL3/4/5-CCR1/5 and TNF–TNFRSF1B signaling." (PMID 36230879, 2022). "In addition, Metadherin on cancer cell surface communicated with CEACAM1 on macrophages to secrete C–C motif chemokine ligand 3 (CCL3), which promotes various tumor types of metastasis." (PMID 36497444, 2022). "We next evaluated whether CCL3 and CCL4 induction was a widespread phenomenon or whether it was only associated to the 4T1 tumor." (PMID 35064009, 2022). "Interestingly, our FACS analysis indicated that CCL3 promoted the transfer of tumor antigens to lymph nodes." (PMID 36654820, 2022). "Particularly, the increase of plasmatic CCL3/MIP-1α in patients with DCB could be a consequence of tumor hypoxia on chemokine production." (PMID 35794623, 2022). "This analysis showed that genes representing T-cell activation and tumor-killing including Ifng, Vcam1, Rgs1, and Il2rb, had higher expression levels, whereas T-cell exhaustion genes such as Tim-3, Ccl3, Rgs2, and Cd6f3, had lower expression levels in Ogr1−/− mice than that in the WT mice." (PMID 34158625, 2021). "Interestingly, a cascade involving CCL2 and CCL3 has been described, in which TAMs, derived from CCL2-recruited MDSCs, secrete CCL3, which further promotes macrophage retention in the tumor and tumor metastatic sites." (PMID 34575965, 2021). "Indeed, IL-37 overexpression in HCC cells is related with the recruitment of more DCs into the tumor tissues by secreting high levels of specific chemokine, such as CCL3 and CCL20, significantly reducing tumor growth." (PMID 34248996, 2021). "Combined with our TAM sub-clustering results, these results indicated that CD86+ TAMs could secrete CCL3 and play a positive role in tumor development." (PMID 33971970, 2021). "Furthermore, we measured the circulatory and tumor associated levels of CCR5 and its ligands (CCL3, CCL4, CCL5) in serum (ELISA), primary tumors (qRT-PCR; IHC) and matched liver metastases (IHC) from CRC patients to assess potential morbidity-related changes." (PMID 32902795, 2021). "The CCL3/4/5 chemokines also directly promote tumor growth and angiogenesis." (PMID 34572138, 2021). "More recently, in a gastric adenocarcinoma mouse model, it was demonstrated that gastric tumor cells produced IL-33, which resulted in mast cell activation that led to the production of macrophage-attracting factors CSF-2, CCL3, and IL-6 and subsequent tumor growth." (PMID 34063789, 2021). "Additionally, LPS-induced proinflammatory markers and chemokines, including CCL3 in dendritic cells is reduced after butyrate treatment, suggesting butyrate influences tumor microenvironment and tumor progression." (PMID 33841394, 2021).